LRP6 (LDL receptor related protein 6)
Diseases named in the same sentence as LRP6 in open-access papers (continued):
Sharing a sentence is not in itself a finding about the gene and the disease.
gastric cancer (10 papers, 2015 to 2024). A primary or metastatic malignant neoplasm involving the stomach. "In SNU1, SNU-5 and AGS human gastric cancer cells, curcumin caused a reduction in Wnt3a, LRP6, phospho-LRP6, β-catenin, phospho-β-catenin, c-Myc and survivin." (PMID 34680593, 2021). "In a study, curcumin suppressed the proliferation of gastric cancer (GC) cells by downregulating the target genes of the Wnt/β-catenin pathway, namely Wnt3a, LRP6, β-catenin, c-myc, and surviving." (PMID 39507759, 2024). "Co-expression of stromal SERPINF1 and tumor cell LRP6, which is one of the ligand–receptor interactions of M2 macrophages and tumor cells, was correlated with lymph node metastasis in gastric cancer samples." (PMID 37333017, 2023). "Subsequently, a confirmation of the suppression of the Wnt/β-catenin signaling pathway by curcumin was provided, showing a decreased expression of Wnt3a, LRP6, phospho-LRP6 and phospho-β-catenin, as well as C-myc, and surviving in gastric carcinoma xenografts." (PMID 37376060, 2023). "Curcumin can promote apoptosis and inhibit gastric carcinoma cell growth through suppression of Wnt3a, LRP6, phospho-LRP6 at Ser1490, β-catenin, phospho-β-catenin at Ser675, C-myc, and survivin proteins involved in the WNT/β-catenin pathway." (PMID 33995644, 2021). "Next, we performed wound healing and migration assays and found that GSK3β, LRP6, or Wnt2 knockdown significantly abolished M hyorhinis‐induced gastric cancer cell motility, but the effect of Wnt2 ablation was less robust than that of the other two factors." (PMID 31321908, 2019). "This miRNA is known to be positively regulated by beta-catenin directly in human gastric cancer and to inhibit the Wnt/beta-catenin pathway in turn by targeting LRP6 in 3 T3-L1 cells." (PMID 25889572, 2015). "Thus, Wnt2, as a ligand of LRP6 in β‐catenin signaling, has a less important role in M hyorhinis‐induced gastric cancer cell motility." (PMID 31321908, 2019). "Targeting the key factors in the β‐catenin signaling pathway, including β‐catenin, GSK3β, and LRP6, could counteract M hyorhinis‐induced gastric cancer cell motility." (PMID 31321908, 2019). "Nevertheless, by identifying the contributing role of β‐catenin, as well as LRP6 and GSK3β, in M hyorhinis‐induced motility, this study may provide valuable evidence for patient‐directed therapies for M hyorhinis‐positive gastric cancer patients." (PMID 31321908, 2019). "Interestingly, an immunoprecipitation assay with a PD4 antibody against the p37 protein detected a complex containing p37 and two upstream regulators of β‐catenin signaling, including GSK3β and the Wnt receptor LRP6,16, 17, 18 in M hyorhinis‐infected gastric cancer cells." (PMID 31321908, 2019). "OSMR, LRP6, and SERPINF1 were expressed in most gastric cancer samples." (PMID 37333017, 2023). "The interaction between SERPINF1 and LRP6 has not been reported in gastric cancer." (PMID 37333017, 2023). "Emerging evidence has demonstrated that Wnt/β‐catenin is activated after gastric cancer and plays a critical role in promoting invasion and migration through overexpressing or increasing the functions of several components of the Wnt pathway such as Wnt1, Wnt2, Wnt3, Wnt5a, Fzd‐3, CTNNB1 and LRP6." (PMID 28994231, 2018).
Oligodontia (10 papers, 2019 to 2026). The absence of six or more teeth from the normal series by a failure to develop. "Herein we aimed to identify novel LRP6 variants in patients with non-syndromic oligodontia (NSO) and perform functional analyses of these variants." (PMID 40534843, 2025). "Two probands with severe oligodontia carried not only LRP6 mutations but also WNT10A pathogenic variants, suggesting a potential mutational synergism or digenic inheritance for WNT signaling-related genes in FTA." (PMID 34834569, 2021). "Finally, genotype-phenotype correlations in LRP6-associated non-syndromic oligodontia (NSO) were systematically investigated." (PMID 40534843, 2025). "In this study, we identified two novel LRP6 mutations in two non-syndromic oligodontia families." (PMID 36143186, 2022). "In this study, we recruited families with non-syndromic oligodontia and identified two novel LRP6 mutations: a de novo frameshift mutation by a 1-bp insertion in exon 9 (c.1870dupA, p.(Met624Asnfs*29)) and a splicing donor site mutation in intron 8 (c.1762+2T>C)." (PMID 36143186, 2022). "Heterozygous loss‐of‐function mutations in LRP6 were found to cause oligodontia in three patients." (PMID 30950205, 2019). "The integration of granular phenotypic characterization with comprehensive genetic analysis, as presented in this study, significantly contributes to a more refined and nuanced understanding of LRP6-related oligodontia." (PMID 41505923, 2026). "In vitro studies further demonstrate that truncated LRP6 proteins inhibit canonical WNT signaling and cause oligodontia." (PMID 40534843, 2025). "The identification of a novel de novo missense variant, c.1231G>T (p.Asp411Tyr) and known missense variant, c.1252T>C (p.Tyr418His) in LRP6 within Thai individuals diagnosed with oligodontia substantially reinforces the indispensable role of LRP6 in orchestrating human dental development." (PMID 41505923, 2026). "These molecular disruptions consistently manifest clinically as severe oligodontia, frequently co-occurring with various ectodermal anomalies, thereby unequivocally underscoring LRP6’s indispensable and dual role in both dental and broader ectodermal development." (PMID 41505923, 2026). "Oligodontia, the congenital absence of multiple permanent teeth, is frequently linked to LRP6 variants." (PMID 41505923, 2026).
osteosarcoma (10 papers, 2017 to 2025). A usually aggressive malignant bone-forming mesenchymal neoplasm, predominantly affecting adolescents and young adults. "Another study demonstrated that circ-LRP6 regulates the miR-141-3p/HDAC4/HMGB1 axis to contribute to osteosarcoma progression." (PMID 40696350, 2025). "In bone cancer, circ-LRP6 suppresses miR-141-3p, which promotes proliferation, migration, and invasion of osteosarcoma cells." (PMID 37511619, 2023). "circ-LRP6 is highly expressed in osteosarcoma (OS) tissues and cell lines and its expression correlates with cell proliferation and a lower overall survival in OS metastatic patients." (PMID 36762207, 2023). "Circ-LRP6 expression was found to be upregulated in osteosarcoma tissues and cell lines in comparison to paracancerous tissues and normal osteoblasts, respectively." (PMID 37511619, 2023). "circ-LRP6 is highly expressed in osteosarcoma tissues and cell lines (OS), and its expression correlates with cell proliferation and lower overall survival in OS metastatic patients." (PMID 36762207, 2023). "CircRNA LRP6 accelerates the development of osteosarcoma through regulating KLF2 and APC expressions." (PMID 33958507, 2021). "In summary we report a novel mechanism where biglycan, an ECM proteoglycan, through a LRP6/β-catenin/IGF-IR axis enhances osteosarcoma cell growth." (PMID 30406034, 2018). "In summary, we report a novel mechanism where biglycan through a LRP6/β-catenin/IGF-IR signaling axis enhances osteosarcoma cell growth." (PMID 30406034, 2018). "In addition, biglycan was shown to control osteosarcoma cell proliferation through a LRP6/β-catenin/IGF-IR signaling axis." (PMID 35267503, 2022). "For example, CircRNA LRP6 promotes osteosarcoma development by targeting KLF2 and APC." (PMID 34224315, 2021). "Thus, it was recently demonstrated that the attenuation of the low-density lipoprotein receptor-related protein 6 (LRP6)-Wnt/β-catenin signaling pathway through microRNA-183 (miR-183) inhibits osteosarcoma cell proliferation and invasion." (PMID 30406034, 2018). "To gain further insights into the functions of LRP6 ubiquitin modifications induced by Itch, we used a doxycycline inducible HA-Ubiquitin expressing human osteosarcoma cell line, U2-OS, in which the expression of endogenous ubiquitin was replaced with HA tagged wild type ubiquitin." (PMID 28966723, 2017). "Circ-LRP6 sponged miR-141-3p, which resulted in higher expression of two targets of this miRNA, HDAC4 and HMGB1, and promoted the proliferation, migration, and invasion of osteosarcoma cells." (PMID 37511619, 2023).
hyperlipidemia (9 papers, 2014 to 2021). "In humans, mutations in the gene encoding LRP6 are associated with hyperlipidemia in humans." (PMID 25414334, 2014). "In summary, the unique role of LRP6 in hepatic lipogenesis and hyperlipidemia has been well established." (PMID 26046396, 2015). "R611C, a rare nonconservative mutant of Lrp6, has been reported to be associated with autosomal dominant atherosclerosis that exhibits hyperlipidaemia and fatty liver disease." (PMID 34671210, 2021). "It has also been shown that oxidized phospholipid levels are high in patients suffering from hyperlipidemia, suggesting that LRP6 may have an important role in the occurrence of osteoporosis via hyperlipidemia." (PMID 34589484, 2021). "As a result, a novel heterozygous variant in exon 6 of LRP6 was identified in a proband, belonging to a patient who was 41 years old and diagnosed with myocardial infarction without hyperlipidemia." (PMID 27455246, 2016). "The magnitude of the observed change in LDL clearance due to malfunctions of mutant LRP6 does not sufficiently explain the severity of hyperlipidemia in mutation carriers." (PMID 26046396, 2015). "The in vivo and in vitro characterization of LRP6 and its mutant forms provided deep insight into its novel roles in regulation of serum LDL and TG and VSMC differentiation and its impaired function as a cause of hyperlipidemia, insulin resistance and VSMC proliferation." (PMID 33969358, 2021). "Furthermore, the communication between LRP6 and nutrient-sensing pathways in particular cholesterol sensing pathway and/or mTOR pathway should be a focal point for novel nutritional interventions against hyperlipidemia and non-alcoholic fatty liver disease." (PMID 26046396, 2015).
liver cancer (9 papers, 2016 to 2025). An epithelial or non-epithelial malignant neoplasm that arises from the liver. "Although a change in LRP6 level/location in the plasma membrane after regulation of GBA1 in liver cancer was observed in this study, the mechanism, such as inhibition of receptor internalisation, needs to be studied in greater depth." (PMID 35637196, 2022). "LRP6 is highly expressed in tumors of liver cancer patients, and overexpression of LRP6 promotes liver cancer cell proliferation and tumor growth." (PMID 34589484, 2021). "The overexpression of LRP6, a co-receptor of the Wnt/catenin pathway, was shown to enhance cancer formation, proliferation, and migration in liver cancer." (PMID 33050615, 2020). "We performed siRNA knockdown of LRP5, LRP6, or β-catenin in liver cancer HepG2 cells to determine the effect on tumor cell proliferation." (PMID 31881970, 2019). "Here, we examined the effect of LRP5, LRP6, or β-catenin knockdown on liver cancer HepG2 cell proliferation." (PMID 31881970, 2019). "Taken together, these results suggest that PGCP knockdown up-regulates Wnt/β-catenin signaling through the induction of LRP6 phosphorylation, leading to increased liver cancer metastasis." (PMID 27806330, 2016). "A constitutively active form of LRP6 promoted cell migration and invasion in liver cancer cell lines, and enhanced tumor formation in vivo via transmembrane transduction of Wnt signals." (PMID 27806330, 2016). "These evidences suggest that PGCP can be a good material for study of liver cancer treatments, because of important roles of LRP6 in liver cancer." (PMID 27806330, 2016). "miR-1269a can down-regulate the expression of SPATS2L and LRP6, thereby inhibiting the proliferation of liver cancer cells; while miR-1269a rs73239138 can inhibit the down-regulation of SPATS2L and LRP6 by miR-1269a to promote the occurrence and development of cancer." (PMID 35252180, 2022). "Finally, expression of long non-coding RNA DLGAP1-AS1 is increased in liver cancer tissue, where it inhibits miR-26a/b-5p, a negative regulator of LRP6 expression." (PMID 34589484, 2021). "Another cancer with which LRP6 is highly correlated is liver cancer." (PMID 34589484, 2021). "Several components are involved in liver cancer progression via regulation of LRP6." (PMID 34589484, 2021). "The expression level of LRP6 is up-regulated in liver cancer." (PMID 27806330, 2016). "Connective tissue growth factor (CTGF) is highly expressed in liver cancer patients, and CTGF promotes phosphorylation of LRP6." (PMID 34589484, 2021). "We demonstrated that knockdown of LRP5, but not LRP6 or β-catenin, markedly inhibited the proliferation of liver cancer HepG2 cells by destabilizing NUP37 and may result in the subsequent destruction of the NPC integrity." (PMID 31881970, 2019). "However, the role of LRP5 and LRP6 in liver cancer has not been fully investigated." (PMID 31881970, 2019).
pancreatic cancer (9 papers, 2016 to 2025). "Research indicates that the overexpression of cytoskeleton-associated protein 4 (CKAP4) or LDL receptor-related protein 6 (LRP6) facilitates the development of pancreatic cancer." (PMID 40066091, 2025). "Previous studies have confirmed that the overexpression of CKAP4 or low-density lipoprotein receptor-related protein 6 (LRP6) promotes the progression of pancreatic cancer." (PMID 40681504, 2025). "Existing research on LRP6 is limited to studies involving epithelial cancers, such as colorectal, liver, breast, and pancreatic cancers, often using immunohistochemical tests or bioinformatic analysis." (PMID 39796676, 2024). "In line with that, LRP6 silencing in human pancreatic cancer cell lines inhibits β-catenin/TCF transcriptional activity and cell proliferation." (PMID 31412666, 2019). "This review summarizes current knowledge regarding the biological function and regulation of LRP6 in the development of epithelial cancers—especially colorectal, liver, breast and pancreatic cancers." (PMID 31412666, 2019). "Furthermore, Pearson's correlation analysis revealed that FGD5-AS1 expression was positively correlated with LRP6 expression and β-catenin expression in pancreatic cancer tissues, whereas miR-577 expression was negatively correlated with them." (PMID 34821374, 2022). "Increased LRP6 expression and phosphorylation associated with β-catenin nuclear accumulation have been observed in human-derived PDAC as well as murine KRAS-dependent pancreatic cancers (KPCs)." (PMID 31412666, 2019). "Notably, the vitamin D analogue calcipotriol, which displays anticancer properties in advanced pancreatic tumours, likely acts by reducing LRP6 protein levels." (PMID 31412666, 2019). "These include the colorectal, gastric, ovarian and pancreatic cancers that harbour inactivating mutations in RNF43 (refs 65, 66, 67, 68, 69, 70), a negative Wnt feedback regulator that promotes degradation of the Wnt co-receptors Frizzled and LRP6 (refs 70, 71, 72)." (PMID 27138857, 2016). "S-palmitoylation promotes the location of CKAP4 and LRP6 within detergent-resistant membrane (DRM) fractions, activating the PI3K-AKT pathway and enhancing pancreatic cancer cell proliferation." (PMID 40066091, 2025). "On the other hand, LRP6 activity is also controlled by LINC01133, a long non-coding RNA upregulated in pancreatic cancers." (PMID 31412666, 2019). "More specifically, the microRNA miR-454, which targets LRP6 mRNA, is downregulated in PDAC and therefore its overexpression in pancreatic cancer cells impairs proliferation, angiogenic activity and metastatic potential." (PMID 31412666, 2019).
Hypercholesterolemia (8 papers, 2014 to 2022). An increased concentration of cholesterol in the blood. "Multiple functional mutations within the LRP6 gene have been identified to be linked to early coronary artery diseases (CAD) with hypercholesterolemia 13, indicating that LRP6 might play a critical role in myocardial infarction pathogenesis." (PMID 33391533, 2021). "The common variant rs10845493 in LRP6 is associated with elevated LDL levels and rs2302685 (p.(Val1062Ile)) is associated with hypercholesterolemia." (PMID 35323704, 2022). "PBLs in young heterozygous genetically characterized FH patients have higher expression of LRP5 and LRP6 than age‐matched healthy controls or patients with secondary hypercholesterolaemia." (PMID 27680891, 2017). "Thus, an oligogenic form of hypercholesterolemia is probably present in this family and high levels of LDL-C could be caused by the cumulative effect of LRP6 and CYP7A1 variants, which is aggravated by the LDLRAP1 variant." (PMID 35323704, 2022).
myocardial infarction (8 papers, 2014 to 2025). Gross necrosis of the myocardium, as a result of interruption of the blood supply to the area, as in coronary thrombosis. "circRNA1615 inhibits ferroptosis via modulation of autophagy by the miRNA152-3p/LRP6 molecular axis in cardiomyocytes of myocardial infarction." (PMID 34712388, 2021). "This study was aimed at exploring the biological function and molecular mechanism of ferroptosis of LRP6 modulation in cardiomyocytes of myocardial infarction (MI)." (PMID 34712388, 2021). "Supporting the idea that increased LRP6/β-catenin due to aggressive mechanical stimulation were associated with cardiomyopathy, the result from immunohistochemistry of isoproterenol-(ISO) induced myocardial infarction animal model showed increased Wnt1 expression compared to that control rat." (PMID 30400259, 2018).
cervical carcinoma (5 papers, 2010 to 2024). A carcinoma arising from either the exocervical squamous epithelium or the endocervical glandular epithelium. "The Wnt signaling pathway, which consists of multiple factors (β-catenin, Dvl2, LRP6, Wnt, Naked, C-Myc and Axin1, etc.)involved in cell proliferation, differentiation, migration, and polarity, is associated with many cancers, including cervical cancer." (PMID 35965516, 2022). "LRP6, a Wnt coreceptor, shows increased expression in cervical cancer and may serve as an oncoprotein by blocking Wnt/β-catenin signaling." (PMID 35965516, 2022). "For example, circ-LRP6 functioned as an oncogenic regulator in esophageal squamous cell carcinoma by targeting the miR-182/Myc signaling and circ-ZNF609 facilitated the development of cervical cancer through the miR-197-3p-mediated E2F6 upregulation." (PMID 34057019, 2021).
dilated cardiomyopathy (5 papers, 2020 to 2024). Cardiomyopathy which is characterized by dilation and contractile dysfunction of the left and right ventricles. "It has been also reported that LRP6 deficiency results in lethal dilated cardiomyopathy and cardiac dysfunction by activation of dynamin-related protein 1 signaling." (PMID 33139721, 2020).
Obesity (5 papers, 2020 to 2024). Accumulation of substantial excess body fat. "LRP6 has been reported to limit obesity by regulating Wnt/β-catenin and subsequently inhibiting adipogenesis." (PMID 38632591, 2024). "In that study, authors reported that LRP6+/− mice on high-fat diet are protected against diet-induced obesity." (PMID 31937343, 2020).